BDNF (brain derived neurotrophic factor)
Diseases named in the same sentence as BDNF in open-access papers (continued):
Sharing a sentence is not in itself a finding about the gene and the disease.
autism (continued). "In the present report, we demonstrate that, in a much larger patient cohort, sAPPα levels are increased and BDNF levels decreased in the plasma of patients with severe autism (determined by CARS score) as compared to controls." (PMID 21731612, 2011). "Further, we find that BDNF levels are decreased in the plasma of patients with severe autism as compared to controls." (PMID 21731612, 2011). "If peripheral BDNF levels correlate well with brain BDNF levels as has been suggested, our finding of decreased plasma BDNF would suggest that BDNF alone cannot account for brain overgrowth in autism." (PMID 21731612, 2011). "We have observed that sAPPα levels are increased and BDNF levels decreased in the plasma of patients with severe autism as compared to controls." (PMID 21731612, 2011). "BDNF is also trophic for serotonergic neurons, and abnormalities in serotonin levels are the most common biochemical findings in autism." (PMID 19582215, 2009). "Larger and more homogeneous populations should be studied to further investigate the relationship between different levels of neurotrophins and growth factors in autism, taking into account confounding factors such as age or platelet-derived production (as in the case of BDNF)." (PMID 40004071, 2025). "In animal models with autism-like behavior, such as BTBR mice and neuroligin 3 (NLG3) loss-of-function mutants, impairments in GABAergic hippocampal synaptic function have been found and directly related to BDNF/TrkB signaling impairments." (PMID 39125882, 2024). "Abnormal cortical developmental was observed in autism children harboring BDNF Val66Met SNP." (PMID 39569070, 2024). "Excess BDNF is also involved in the pathogenesis of mania and autism." (PMID 39727635, 2024). "The BDNF was significantly reduced in the autism-induced rats." (PMID 38344592, 2024). "Since BDNF is necessary for the development and operation of neurons, reduced levels in the autism group as reported in this study may lead to aberrant synapse formation, which manifests as a neurodevelopmental disorder." (PMID 38344592, 2024). "Furthermore, we have identified that diminished activity-dependent BDNF signaling differently affects the severity of autism-like behavioral deficits in males and females, revealing previously underappreciated sex-specific effect in ASD." (PMID 37205980, 2023). "Whether high levels of BDNF in M2 macrophages are associated with reduced sociability remains unclear; however, BDNF abnormalities have been identified in humans with autism spectrum and posttraumatic stress disorders." (PMID 37461488, 2023). "We therefore hypothesize that diminished activity-dependent BDNF signaling could confer autism-like behavioral deficits." (PMID 37205980, 2023). "The relation of BDNF with autism has been evaluated in a number of studies on ASD patients." (PMID 37239153, 2023). "Notably, diminished activity-dependent BDNF signaling differentially resulted in autism-like social deficits and increased self-grooming in male and female mice, and male mice were more severe than female mice." (PMID 37205980, 2023). "Moreover, taking into account behavioral and neuroanatomical similarities of this animal model and ASD in humans, we believe that BDNF can be considered a target for autism treatment." (PMID 37239153, 2023). "Previous articles have reported that BDNF is related to the occurrence and development of autism." (PMID 35465089, 2022). "This suggests that the normalization of BDNF levels by mood-stabilizing drugs in subjects with autism may include a reduction in proBDNF, which represents a portion of total BDNF levels." (PMID 35962006, 2022). "Furthermore, brain-derived neurotrophic factor (BDNF, OMIM #113505) has been proven to be associated with intellectual disability, autism, and childhood-onset obesity in subjects with WAGR." (PMID 36011342, 2022).
autism (continued). "In our recent study, we observed the beneficial effect of oxytocin on the improvement of autistic-like behaviors with an effect on brain plasticity along with a decrease in plasma BDNF (brain derived neurotrophic factor) levels in a maternal separate rat model of autism." (PMID 33503967, 2021). "Importantly a significant correlation between the severe form of autism and higher level of peripheral BDNF level was reported." (PMID 33503967, 2021). "Low zinc levels may contribute to the development of autism through abnormal function of the zinc-metalloproteinase-brain-derived neurotrophic factor (BDNF) axis." (PMID 34073785, 2021). "Thus, the mouse in models of autism demonstrating dysfunctional BDNF secretion would serve as good targets for initial evaluation of the ‘rubber tail illusion’." (PMID 31101876, 2019). "The molecular changes reported here may help to explain the cognitive and behavioral signs of autism and reinforce BDNF as a potential molecular target for this neurodevelopmental disorder." (PMID 31787877, 2019). "Likewise, genes linked to ADHD (LPHN3), autism (YWHAZ), and depressive behavior (BDNF) also control neuronal fate within different brain regions." (PMID 30112632, 2019). "Therefore, among the various mouse models of autism, the Caps2-KO mouse, which exhibit impairments in BDNF release, represents a suitable first target for evaluating body ownership using the rubber tail task." (PMID 31101876, 2019). "Thus, a comprehensive evaluation of the local changes of hippocampal BDNF isoforms in the VPA-model of autism is necessary to understand the genesis of the altered connectivity in the ASD brain." (PMID 31787877, 2019). "In addition to an imbalance in BDNF isoforms in autism, there is also an imbalance in TrkB isoforms." (PMID 29691724, 2018). "Brain-derived neurotrophic factor serum levels are significantly increased in autism." (PMID 28751869, 2017). "In a sample of autistic patients, it was suggested that an imbalance in BDNF isoforms may have been a possible mechanism leading to autism." (PMID 29258453, 2017). "The down-regulation of BDNF-Akt-Bcl2 anti-apoptotic signaling pathway could be responsible for pathogenesis of autism." (PMID 27917343, 2016). "Several studies have indicated that BDNF plays a significant role in the neurobiology of autism." (PMID 26866045, 2015). "Interestingly, we found that the levels of pro-BDNF, the precursor to mature BDNF, were increased in sera from children with autism." (PMID 25769033, 2015). "The correlation between high psychomotor activity level and elevated BDNF serum levels found in this pilot study may have relevance for hyperactivity related to autism and warrants further investigations." (PMID 26866045, 2015). "Our data which is based on ~5year old children suggest that BDNF levels are decreased in autism, and this may contribute to abnormalities in neurogenesis and synaptogenesis and synaptic plasticity in autism." (PMID 25769033, 2015). "Based on this, we can speculate that the protective effect of P6 against autism serum-induced neurodegenration and oxidative stress could have been mediated via BDNF." (PMID 25769033, 2015). "For example, serum level of BDNF, which plays an essential role in brain development, neurogenesis and synaptogenesis, and synaptic plasticity, was shown to be decreased in children, adolescents, and adults with autism." (PMID 25769033, 2015). "Besides BDNF, we also observed abnormalities in the serum levels of various other neurotrophic factors in children with autism." (PMID 25769033, 2015). "Since autism is a neurodevelopmental disorder that begins in childhood and brain-derived neurotrophic factor (BDNF) is important in neurodevelopment, early BDNF hyperactivity may play a role in the pathogenesis of autism." (PMID 25530675, 2014).
autism (continued). "BDNF is a growth factor which may be related to the increased brain volumes seen in some young children with autism." (PMID 25126406, 2014). "Interestingly, an altered balance of the processing of BDNF in autism was demonstrated recently by studies of the fusiform gyrus of the brain of patients with autism that disclosed abnormal processing of the pro- and truncated-BDNF forms." (PMID 23566357, 2013). "Brain-derived neurotrophic factor (BDNF) in brain in some children with autism is reduced." (PMID 22846252, 2012). "This led to the hypothesis that elevated BDNF in the CNS may contribute to brain overgrowth observed in autism." (PMID 21731612, 2011). "The present study suggests that BDNF may play a role in the pathogenesis of autism through its neurotrophic effects on central nervous system." (PMID 19582215, 2009). "We suggest that BDNF has a possible role in the pathogenesis of autism." (PMID 19582215, 2009). "The sex differences of intrinsic excitability of pyramidal neurons in the PFC of male and female BDNF+/Met mice may partially contribute to the severe autism-like behavioral deficits in male BDNF+/Met mice and support that males are more vulnerable to having ASD." (PMID 39569070, 2024). "The higher expression of BDNF is consistent with higher expression of this gene reported in multiple studies of autism, including two meta-analyses, as well as the increased brain size and the number of neuronal cells and their processes observed in the early age of patients with autism." (PMID 38994948, 2024). "Here, we investigated the effect of diminished activity-dependent BDNF signaling on autism-like behavioral deficits by using mice with genetic knock-in of a human BDNF methionine (Met) allele, which has decreased activity-dependent BDNF release without altering basal BDNF level." (PMID 37205980, 2023). "The sexual differences in social behavioral deficits and self-grooming between male and female BDNF+/Met mice indicate neuronal estrogen in the brain may contribute the milder autism-like behavioral deficits in female BDNF+/Met mice, which needs to further be investigated." (PMID 37205980, 2023). "Moreover, early brain-derived neurotrophic factor (BDNF) hyperactivity may play an etiological role in autism as serum BDNF levels positively correlate with the cortical BDNF levels and have increased values in autism." (PMID 37232860, 2023). "Autism could be a disease where there is a role for several neurotransmitters including BDNF." (PMID 35465089, 2022). "Interestingly, abnormalities in the ratio of pro-BDNF/mature BDNF has been described in the brain of individuals with autism, suggesting that the balance between these isoforms could be associated with the disease." (PMID 31024262, 2019). "Thus, our rat model of autism also successfully reproduced the BDNF disturbance found in patients." (PMID 31036753, 2019). "In addition, it was suggested that disruption of brain-derived neurotrophic factor (BDNF) activity through tyrosine kinase B (TrkB) signaling might play a role in autism initiation and propagation." (PMID 30804889, 2019). "However, in spite of the abundant literature that relates BDNF levels with autism in different ways, the precise role of BDNF in this type of disorder remains unclear." (PMID 31787877, 2019). "Interestingly, BDNF levels have also been associated with ASD-like traits in the general population, and recent meta-analysis studies suggest that BDNF levels may be considered as a possible biomarker for autism." (PMID 31787877, 2019). "Because BDNF/TrkB-mediated signaling pathways, including Akt-mTOR and Eps8-Rac, play a key role in the development of the cortex and in synaptic function and plasticity, altered BDNF/TrkB signaling through these pathways may be an important contributor to autism pathogenesis." (PMID 29691724, 2018). "Finally, we analyzed BDNF levels in the sera from autism patient cohort." (PMID 26728085, 2016).
autism (continued). "Therefore, patients with severe autism (CARS ≥37) show low levels of IL-18 but high levels of BDNF." (PMID 26728085, 2016). "Das reported that in children with autism, BDNF plasma levels were significantly lower compared to healthy controls and it was hypothesized that apoptosis may play a role in the BDNF-Akt-Bc12 anti-apoptotic signaling pathway as a mechanism contributing to the pathology of AD." (PMID 26866045, 2015). "BDNF has reported links to autism and may have functional roles similar to sAPPα." (PMID 21731612, 2011). "In contrast to BDNF and IL6, we observed decreased expression of IFI16, an anti-inflammatory gene, in the NSCs of patients with autism." (PMID 38994948, 2024). "Our work demonstrates the positive therapeutic effect of BDNF delivered by FUS non-invasively across the BBB into the PFC in a rat model of autism, offering a potential strategy for treating autism." (PMID 36117626, 2022). "Our study showed that PPA treatment significantly decreased the expression of MMP-9, BDNF, ICAM, Synapsin I, PSD-93, and PSD-95 but elevated GFAP in the brain of PPA-induced PPA-induced autism-like rats." (PMID 35334937, 2022). "The current study aimed to compare BDNF, proBDNF and IGF-1 serum levels between children aged 5–15 years old with mild to moderate autism and controls." (PMID 35962006, 2022). "Candidate genes such as BDNF, ELP4, PRRG4, and SLC1A2 have been identified in relation to autism, cognitive/developmental delays, and behavioral problems." (PMID 34970513, 2021). "Brain Derived Neurotrophic Factor (BDNF), a key multifunctional regulator of brain development, has been related to autism in several ways." (PMID 31787877, 2019). "The possible role of BDNF dysregulation in FXS and autism has been pioneered by the Castrén lab (Castrén and Castrén, 2014)." (PMID 30899214, 2019). "Conversely, the levels of pro-BDNF, FGF-2, and LIF were found to be increased in autism sera compared to control (pro-BDNF, Student’s t-test, p = 0.0043; LIF, Student’s t-test, p = 0.0216; FGF-2, Student’s t-test, p = 0.0194)." (PMID 25769033, 2015). "The levels of mature CNTF and BDNF were markedly decreased in autism sera (CNTF, Student’s t-test, p = 0.0026; BDNF, Student’s t-test, p = 0.0003)." (PMID 25769033, 2015). "Contrarily, few studies have reported increased BDNF serum levels in patients with autism (particularly during the early neonatal period), and an increase in BDNF levels during early developmental stages has been speculated to contribute to the pathophysiology of autism." (PMID 25769033, 2015). "Recently, a relationship has been suggested between BDNF, sonic hedgehog (SHH), and oxidative stress in autism." (PMID 25769033, 2015). "Proteomic profiling studies have shown that brain-derived neurotrophic factor (BDNF) and glial fibrillary acidic protein (GFAP) are altered in autism patients." (PMID 25126406, 2014). "Indeed, a recent study has found decreased BDNF levels in the brains of autistic patients as compared to controls and has suggested this may lead to reduced BDNF-Akt-Bcl2 anti-apoptotic signaling in autism." (PMID 21731612, 2011). "On the other hand, BDNF expression was increased in the NSCs and astrocytes of patients with autism but not in neurons, and its expression in astrocytes was 5- and 3-fold higher than NSCs and neurons, respectively." (PMID 38994948, 2024). "Rats with autism had a significant decrease in GABA and BDNF levels." (PMID 38344592, 2024). "Without more detailed research on BDNF expression in the brain, it is difficult to make conclusions about the correlation between autism and peripheral BDNF levels." (PMID 37239153, 2023). "The behavioral impact of diminished activity-dependent BDNF signaling on autism has not been evaluated and should be addressed to demonstrate its etiological role in ASD." (PMID 37205980, 2023). "Total BDNF levels in subjects with autism were similar to controls, regardless of medication status." (PMID 35962006, 2022).
autism (continued). "Counter-intuitively, the one subject in our study treated with VPA exhibited the lowest BDNF levels of any of the autism subjects but did not exhibit unusual proBDNF levels." (PMID 35962006, 2022). "The Shapiro–Wilk normality test revealed that no variables except age, CARS scores and BDNF were normally distributed within the autism group (n = 22)." (PMID 35962006, 2022). "BDNF levels in the brain of animal models of autism have shown unclear results ranging from no change, increase, or decrease." (PMID 34439657, 2021). "We feel that the value of BDNF as a marker is relative: if a child displays a classical clinical picture of ASD with normal or decreased blood levels of BDNF, the diagnosis of autism will certainly not be excluded." (PMID 33060610, 2020). "BDNF levels are positively correlated with autism traits, by the Autism Quotient questionnaire, in a non-clinical population." (PMID 31548888, 2019). "Lastly, Eps8 protein, which is downstream of BDNF and activates the Rac pathway important for synaptic plasticity, is decreased in idiopathic autism, and knockout of Eps8 in a mouse model resulted in spine abnormalities, decreased LTP and autism-like behavior." (PMID 29691724, 2018). "In children in the autistic spectrum and in those with mental retardation without autism, elevated levels of the neurotrophin brain-derived neurotrophic factor (BDNF) were measured." (PMID 29904026, 2018). "The mRNA level of BDNF was significantly lower in autistic sera treated rat brains compared to sham and control sera treatment groups (ANOVA, p = 0.0006; sham vs. autism group, Bonferroni’s post-hoc test, p<0.01; autism serum vs. control serum group, Bonferroni’s post-hoc test, p<0.01)." (PMID 25769033, 2015). "Interestingly, the expression of NTRK2 (a receptor for BDNF), with almost 3-fold greater expression in astrocytes vs. neurons, exhibited a 30-fold decrease in the astrocytes of patients with autism vs. controls (p = 0.01), but not in neurons or NSCs." (PMID 38994948, 2024). "On the other hand, the crosstalk between BDNF and the DA system in autism has not been studied yet." (PMID 37239153, 2023). "BDNF levels were significantly higher compared with age-matched controls without autism." (PMID 37762342, 2023). "Moreover, BDNF expression levels in the ACC were decreased in our study, which is consistent with other studies that have reported that BDNF expression decreases in the prefrontal cortex, hippocampus, and other regions of the brain in a VPA-exposed autism model." (PMID 35465089, 2022). "Reports of altered BDNF in autism have most commonly found elevated values from normal." (PMID 26866045, 2015). "Our data indicate that expressions of BDNF, Grm3, Foxp1, Auts2 and Shanks3 in the hippocampus are significantly induced by L-serine administration in GHRH-KO mice via changed expression of epigenetic markers, which may ameliorate impairment of memory and autism-related behavior." (PMID 36672612, 2022). "While minocycline did not have a significant effect on core autism symptoms and adaptive functioning, it significantly reduced IL-8, an anti-inflammatory cytokine, and brain-derived neurotrophic factor (BDNF) in the CSF, and BDNF level (as normalized by alpha-2 macroglobulin level) in serum." (PMID 31824351, 2019). "BDNF and IGF-1 measures from many of the subjects with autism were previously published as part of an analysis of non-invasive brain stimulation effectiveness in these patients." (PMID 35962006, 2022). "Through its neuroprotective and antioxidant effects independent of BH4 and BDNF, MOTS-c may alleviate autism-like behaviors, suggesting its potential as a therapeutic candidate for ASD." (PMID 41706383, 2026). "ProBDNF levels have not been measured in peripheral blood of subjects with autism, whereas BDNF immunoreactivity measured by ELISA in peripheral blood of children with autism compared to controls has resulted in mixed findings." (PMID 35962006, 2022).